PEA15 (proliferation and apoptosis adaptor protein 15)
Diseases named in the same sentence as PEA15 in open-access papers (continued):
Sharing a sentence is not in itself a finding about the gene and the disease.
thyroid tumor (1 paper, 2022). A benign or malignant neoplasm affecting the thyroid gland. "In CD95-resistant thyroid tumor cells, both PEA-15 and c-FLIP mRNA expressions are up-regulated through interleukin-4 (IL-4) and IL-1037." (PMID 34997083, 2022).
tumor (26 papers, 2014 to 2026). "In astrocytoma, PEA-15 levels were inversely associated with the stage of the tumour." (PMID 24657708, 2014). "After systematic data curation, four upregulated (YWHAB, TXNDC12, MYL6B, SFN) and four downregulated (FN1, PSMB6, PRDX4, PEA15) markers in miRNA-overexpressed tumor secretomes were identified." (PMID 37128318, 2023). "Proliferation and apoptosis adaptor protein 15 (PEA15) expression was weakly positive in normal renal tissues but moderately or strongly positive in tumor tissues according to HPA070820 staining." (PMID 37056387, 2023). "Altogether, our results provide evidence for the prevention of tumor angiogenesis through the repression of PEA15, PPP1CA and TUFT1 demonstrating the importance of their downregulation by miR-449a-5p." (PMID 34976171, 2022). "Our results show that PEA15 phosphorylation status serves as an important regulator for PEA15’s dual role as an oncogene or tumor suppressor and support the potential of PEA15-AA as a therapeutic strategy for treatment of TNBC." (PMID 34241740, 2021). "In vivo mouse models were used to determine the effects of PEA15 phosphorylation on tumor growth and metastasis." (PMID 34241740, 2021). "PEA15 overexpression significantly inhibited tumor growth and suppressed DNA synthesis in a TNBC xenograft model." (PMID 34241740, 2021). "To identify the most tumor-suppressive form of PEA15, we examined the effects of PEA15-AA- and PEA15-DD-overexpressing stable MDA-MB-468 cells in vivo by injecting them into the mammary fat pads of NOD/SCID mice." (PMID 34241740, 2021). "Taken together, our results show that PEA15 phosphorylation status serves as an important regulator, having dual roles as an oncogene or tumor suppressor." (PMID 34241740, 2021). "MiR-132 reduced tumor cell proliferation and invasion, while increased apoptosis by targeting PEA-15 in astrocytoma." (PMID 34419060, 2021). "We further found that nonphosphorylatable PEA15-AA inhibited formation of mammospheres and showed a decrease in mesenchymal markers in vitro and decreased tumor growth and lung metastasis in vivo when compared to phosphomimetic PEA15-DD." (PMID 34241740, 2021). "Consistent with the data from the TCGA, GEO and Oncomine databases, the expression level of PEA15 was remarkably up-regulated in tumor tissues compared to adjacent normal tissue." (PMID 32047549, 2020). "A previous study reported that PEA15 was highly expressed in the cytoplasm and nucleus of tumor cells and induced autophagy in human cells." (PMID 32047549, 2020). "Unphosphorylated PEA-15 can act as a tumor-suppressor, whereas phosphorylation fine-tunes its interaction with other factors to promote tumor development." (PMID 32047549, 2020). "The results revealed that the expression level of PEA15 was significantly increased in tumor tissues compared with normal tissues in all independent datasets." (PMID 32047549, 2020). "The results warrant further evaluation of the phosphorylation state of PEA-15 in order to consider it as a potential biomarker of tumour sensitivity to cisplatin." (PMID 32102425, 2020). "Hsa-miR-212 is a tumor suppressor microRNA which negatively regulates anti-apoptotic protein PED/PEA-15." (PMID 30669618, 2019). "The hallmark of upregulated CMA activity in most cancer types enhances oncogenesis by shifting the balance of PEA-15 phosphorylation homeostasis toward tumor promotion." (PMID 26263999, 2015). "The roles of PEA-15 in enhancing or impairing tumorigenesis depend on active signaling pathways and phosphorylation homeostasis in specific tumor cells." (PMID 26263999, 2015). "Overall, this provides evidence for the role of PEA-15 as both tumour suppressor and tumour promoter in cancer." (PMID 24657708, 2014). "On the other hand, PED/PEA-15 modulates tumor cell survival and contributes to resistance to chemotherapy, interfering with apoptotic pathways." (PMID 25489735, 2014).
tumor (continued). "PEA-15 also regulates cellular invasion in colorectal carcinomas and was observed in well differentiated tumour areas." (PMID 24657708, 2014). "The PEA15 protein associates with ERK in the cytoplasm, restricting its nuclear entry, thus functioning as a tumor suppressor." (PMID 25096718, 2014). "In contrast to its tumour suppressing function, there is now mounting evidence for an oncogenic role of PEA-15 in several cancer types." (PMID 24657708, 2014). "This would suggest the potential for PEA-15 as a tumour suppressor and prognostic marker in cancer with the phosphorylation status of PEA-15 thought to be influential in regulating the function of PEA-15." (PMID 24657708, 2014). "PED/PEA-15 functions either as a tumor-promoter or as a tumor-suppressor, regulating both proliferation and apoptosis." (PMID 25489735, 2014). "PEA-15 is an anti-apoptotic factor involved in TRAIL resistance of tumor cells." (PMID 34419060, 2021). "We found that the nonphosphorylatable mutant PEA15-AA prevented formation of mammospheres and expression of EMT markers in vitro and decreased tumor growth and lung metastasis in in vivo experiments when compared to control, PEA15-WT and phosphomimetic PEA15-DD." (PMID 34241740, 2021). "Moreover, the tumor tissues of PEA15, p-PEA15 (Ser116) and p-PEA15 (Ser104) were stained more deeply in the ZNF703-overexpressing group than in the control group." (PMID 33246486, 2020). "PEA-15 may function as a tumour promoter or suppressor, regulating both proliferation and apoptosis." (PMID 32102425, 2020). "In addition, the authors demonstrated that the conjugation of miR-212 to GL21.T efficiently inhibits the anti-apoptotic protein PED/PEA-15 (15 kDa Phosphoprotein Enriched in Astrocytes), involved in the tumor resistance to chemotherapy treatment." (PMID 31861156, 2019). "Phosphorylation of PEA-15 seems to switch PEA-15 from a tumor-suppressor to a tumor-promoter." (PMID 26263999, 2015). "Sulzmaier and colleagues suggested that the switch between these two states was due to the phosphorylation status of PEA-15 with unphosphorylated PEA-15 demonstrating tumour suppressor qualities while phosphorylation of PEA-15 induced higher tumour cell survival and resistance to apoptosis." (PMID 24657708, 2014). "However, phosphorylation of PEA15 leads to changes in its binding partners, and converts it into a tumor promoter." (PMID 25096718, 2014). "The anti-apoptotic protein, PEA-15 has been implicated in TRAIL resistance as well as insensitivity to other forms of apoptosis in several cancer types resulting in increased cell survival and tumour formation." (PMID 24657708, 2014). "Hence, PEA15 phosphorylation status plays a critical role in the cancer development and metastasis by determining whether PEA15 acts as either an oncogene or a tumor suppressor." (PMID 34241740, 2021). "Loss-of-function mutations in tumor suppressors, such as PTEN and PP4, and over-activation of protein kinases, such as Akt and PKC, identified in many cancer types, could significantly modulate PEA-15 homeostasis in cells." (PMID 26263999, 2015). "The results show that BRAF, CDKN1A, DIABLO, PEA15, ERRFI1, and RPS6KB1 are highly expressed in tumor cell lines, which is the same as in the TCGA database." (PMID 39239554, 2024). "Overexpression of PEA15, PPP1CA and TUFT1 and a related poorer outcome have also been observed in other tumor entities 35-37." (PMID 34976171, 2022). "In other words, unphosphorylated PEA-15 is a tumor suppressor as it inhibits ERK-dependent proliferation, while the doubly phosphorylated protein becomes a tumor promotor as it blocks apoptosis." (PMID 34997083, 2022). "The ACACA, AR, MAPK, PDK1, PEA15, and SYK showed significant differential expression between normal tissues and tumor tissues (P < 0.0001)." (PMID 33842538, 2021). "PEA15 plays a critical role in restricting extracellular signal-regulated kinase (ERK) in the cytoplasm, thus functioning as a tumor suppressor." (PMID 25096718, 2014).
tumor (continued). "We previously found that a nonphosphorylatable mutant of PEA15 inhibited ovarian cancer cell proliferation and tumor growth through partial inhibition of the β-catenin signaling pathway." (PMID 34241740, 2021). "Both EGFR tyrosine kinase inhibitor, erlotinib, and MEK inhibitor, selumetinib (AZD6244), significantly suppress tumor growth and induce G1 arrest in a CCC xenograft model in a PEA-15 dependent manner, and knockdown of PEA-15 results in selumetinib-resistant cells." (PMID 26263999, 2015). "In addition, nonphosphorylatable PEA-15 S104A/S116A mutant (PEA-15-AA) exerts a more potent inhibition of tumor cell migration and in vivo angiogenesis than does phosphomimetic S104D/S116D mutant (PEA-15-DD)." (PMID 26263999, 2015). "Non-phosphorylated, tumor suppressing form of PEA-15 seems to be more susceptible to CMA, by which non-phosphorylated PEA-15 is preferentially targeted by chaperone protein, Hsc70, and transported across the lysosomal membrane for degradation, while doubly phosphorylated PEA-15 is resistant to CMA." (PMID 26263999, 2015).
cancer (18 papers, 2009 to 2025). A tumor composed of atypical neoplastic, often pleomorphic cells that invade other tissues. "On the other hand, in other cancer types, PEA15 expression has been linked with poor prognosis and promoted metastasis." (PMID 34241740, 2021). "PEA15 is a 15 kDa multifunctional phosphoprotein involved in various biological processes, such as the proliferation and apoptosis of cancer cells." (PMID 37056387, 2023). "So far, a number of studies have revealed that high expression of PEA15 protein influences the characteristics of tumors, differentiation degree, prognosis of cancer, and response to chemoradiotherapy." (PMID 32047549, 2020). "ChIP-Seq identified multiple regulatory targets of ZNF703, of which ZNF703 directly binds to the enhancer region of PEA15 to promote the transcription of PEA15 and thereby promoted the proliferation of cancer cells." (PMID 33246486, 2020). "In recent years, studies have found that the expression of PEA15 is closely related to several types of cancers." (PMID 32047549, 2020). "This unbalanced kinase/phosphatase activities cause significant increase in phosphorylated contents of PEA-15, lead to uncontrolled MAPK/ERK-dependent malicious cell proliferation and resistance to chemotherapy-induced cancer cell death." (PMID 26263999, 2015). "PEA-15 is an endogenous protein that has been clinically proven to be beneficial to patients of various cancers." (PMID 26263999, 2015). "Although earlier studies have investigated the function of PEA-15 in astrocytes, this relates mostly to cellular signalling effects on proliferation and apoptosis predominantly with relevance to cancer." (PMID 24657708, 2014). "The signaling of PEA-15 is also actively involved in cancer development and progression." (PMID 36671013, 2023). "Thus, we performed the RT2 Profiler Human Cancer Inflammation and Immunity Crosstalk PCR Array to analyze the gene expression changes that occur as a result of phosphorylation status of PEA15." (PMID 34241740, 2021). "The roles of PEA15 in cancer development are complicated and controversial." (PMID 34241740, 2021). "MAPK, PEA15, and PDK1 were closely associated with cancer metastasis." (PMID 33842538, 2021). "PEA15 (Proliferation And Apoptosis Adaptor) is a 15kDa multifunctional phosphoprotein involved in various essential biological processes such as proliferation and apoptosis of cancer cells." (PMID 32047549, 2020). "Another approach could be promotion of dephosphorylation of PEA-15, which requires enhanced activity or induced overexpression of related phosphatases, whose expression is commonly suppressed in many cancer types." (PMID 26263999, 2015). "The roles of PEA-15 in cancer development and progression are complex and controversial." (PMID 26263999, 2015). "This reveals the potential for PEA-15 to be utilised as either a prognostic marker or a therapeutic target in specific cancer subsets which could be dependent, in part, on the phosphorylation status of the protein." (PMID 24657708, 2014). "Akt, which phosphorylates and stabilises the anti-apoptotic action of PEA-15, is also upregulated in a number of human cancers, suggesting that they might function cooperatively in tumorigenesis." (PMID 19539371, 2009). "PEA-15 interactions with FADD and procaspase-8 can also be targeted to induced apoptosis of cancer cells." (PMID 26263999, 2015). "PTEN activation and PEA-15 dephosphorylation promote Fas-induced apoptosis by releasing FADD, and suppress ERK dependent proliferation in cancer cells." (PMID 26263999, 2015). "Another ubiquitously conserved serine/threonine phosphatase, PP4, strongly affects phosphorylation at Ser116 of PEA-15, through which PP4 regulates apoptosis and proliferation of human cancer cells." (PMID 26263999, 2015).
cancer (continued). "Considering the intracellular role that PEA-15 has in regulating proliferation and apoptosis, it is perhaps not surprising that, in addition to cancer, this phosphoprotein could be involved in other diseases where similar cellular processes occur." (PMID 24657708, 2014).
cardiovascular disease (3 papers, 2014 to 2025). "In cardiovascular disease, our recent study has indicated that PEA-15 may regulate VSM cell proliferation and could therefore be involved in restenosis following angioplasty in the treatment of atherosclerosis." (PMID 24657708, 2014).
neurological disorders (3 papers, 2014 to 2025). "The authors termed this a “nodal” protein indicating that PEA-15 sits at a critical convergence in intracellular signalling (as reviewed above) associated with a range of neurological disorders." (PMID 24657708, 2014).
malignant carcinoma (1 paper, 2020). "We then analyzed the expression of PEA15 protein in 20 normal ovarian tissues and 171 cases of malignant carcinoma tissues by immunohistochemistry." (PMID 32047549, 2020). "Results revealed that PEA15-pSer104 and PEA15-pSer116 were highly expressed in malignant carcinoma." (PMID 32047549, 2020).
metabolic disease (1 paper, 2021). A congenital disorder (due to inherited enzyme abnormality) or acquired (due to failure of a metabolically important organ) disorder resulting from an abnormal metabolic process. "The intracellular protein, phosphoprotein enriched in astrocytes (PEA)-15 has been linked to metabolic disease but its role in lipid storage has not been examined." (PMID 33772049, 2021).
PEA15 also shares sentences with these, for which no sentence is quoted: gastric cancer (2 papers); infection (2); adenopathy (1); cervical cancer (1); Cognitive decline (1); colorectal (1); dementia (1); Hyperglycemia (1); hyperinsulinism (1); hypopharyngeal cancer (1); leukemia (1); liposarcoma (1); lung adenocarcinoma (1); muscular dystrophy (1); neurodegenerative disease (1); prostate carcinoma (1); schizophrenia (1); status epilepticus (1); stomach cancers (1); thyroid cancer (1); vascular insufficiency (1).